KIT (KIT proto-oncogene, receptor tyrosine kinase)
Diseases named in the same sentence as KIT in open-access papers (continued):
Sharing a sentence is not in itself a finding about the gene and the disease.
infarction (8 papers, 2012 to 2025). A localised pathological necrosis of tissue resulting from obstruction of the blood supply usually by a thrombus, an embolus, or vascular torsion. "Moreover, Metrnl-deficient mice failed to mount this KIT-dependent angiogenic response and developed severe post-infarction heart failure." (PMID 39548113, 2024).
mesothelioma (8 papers, 2007 to 2023). A usually malignant and aggressive neoplasm of the mesothelium which is often associated with exposure to asbestos. "Inaddition, SCF/c-Kit/Slug mediates drug resistance in human mesothelioma cells.Knockdown of c-Kit/KIT or SNAI2 increases thesensitivity of mesothelioma cells to the chemotherapeutic agents doxorubicin,paclitaxel, and vincristine." (PMID 33959388, 2021).
testicular seminoma (8 papers, 2007 to 2025). A malignant germ cell tumor arising from the testis. "Mutations in KIT were clustered primarily in exon 17, in a pattern similar to that previously reported in testicular seminomas and intracranial GCTs 14,15." (PMID 39461959, 2024). "Noteworthy is that activating c-KIT mutations have been found in a subset of tumors showing the same histology as testicular seminoma, namely; mediastinal seminomas, intracranial germinomas and ovarian dysgerminomas." (PMID 22937135, 2012). "Activating c-KIT mutations (exons 11 and 17) are found in 10–40% of testicular seminomas, the majority being missense point mutations (codon 816)." (PMID 22937135, 2012). "Furthermore, KIT pathogenic variants associated with tumor development are found in 10–40% of testicular seminomas." (PMID 37575996, 2023). "The presence of activating mutations of c-KIT in testicular seminomas is well known." (PMID 22937135, 2012). "By IHC, these cells showed diffuse positivity for GCT markers including OCT3/4, SALL4, CD117 (c-KIT) and D2-40, corroborating the diagnosis of metastatic testicular seminoma, while CAM 5.2, CK AE1/AE3, glypican 3 and β-HCG highlighted the syncytiotrophoblastic cells." (PMID 38236556, 2024).
cholangiocarcinoma (7 papers, 2017 to 2025). A carcinoma that arises from the intrahepatic biliary tree (intrahepatic cholangiocarcinoma) or from the junction, or adjacent to the junction, of the right and left hepatic ducts (hilar cholangiocarcinoma). "Regarding cholangiocarcinoma, HRAS, KIT and FAS have previously been associated with cholangiocarcinoma in the literature." (PMID 28178311, 2017). "Examining cholangiocarcinoma, we observed that the HRAS, KIT, ZBTB16, FAS and NCOA4 genes were altered by high methylation (shown in light sea green)." (PMID 28178311, 2017). "Furthermore, correlation analysis using cholangiocarcinoma datasets from The Cancer Genome Atlas (TCGA-CHOL) showed that WNT pathway genes (AXIN2, CTNNB1, LEF1) positively correlated with TIC signature genes (KIT, SALL4, CD44, SOX2)." (PMID 39774471, 2025).
colitis (7 papers, 2012 to 2024). Inflammation of the colon. "During the remission phase of colitis, the crypt architecture and pathological score of reconstituted mice was more similar to WT than to KIT Wsh mice at the same time point." (PMID 30518915, 2018). "Body weight loss with WT mice treated with blocking anti-ST2 antibody was comparable to KIT Wsh mice in the acute and recovery phases of colitis." (PMID 30518915, 2018). "To formally assess the role of MC-dependent IL-33/ST2 signals in intestinal homeostasis, we explored if absence of the IL-33-mediated signaling pathway promoted colitis recovery in MC-deficient KIT Wsh or WT mouse models." (PMID 30518915, 2018). "We detected significantly increased T1/ST2 expression in WT but not KIT Wsh mice during the remission phase of DSS-induced colitis." (PMID 30518915, 2018). "However, we did not observe significant differences in colitis degree between groups with or without ST2 blocking in KIT Wsh mice." (PMID 30518915, 2018).
deafness (7 papers, 2013 to 2026). An inherited or acquired condition characterized by the complete loss of the ability to hear from one or both ears. "We determined that deafness is genetically linked to the triallelic KIT variant, which quantifies the qualitative observation that all deaf cats carry at least one W allele." (PMID 25085922, 2014). "It is interesting that the deafness was occurred in a family member (the individual II:1 who most probably carried the KIT mutation (c." (PMID 24000325, 2013). "Further study for delineation of the deafness and KIT mutation is needed in the future." (PMID 24000325, 2013). "It is then probably that such kind of deafness with low-penetrance in the KIT heterogeneous-mutated patients may attributes to the different gene background of each individual." (PMID 24000325, 2013). "However, the previously study by Spritz and Beighton had illustrated a heterogeneous KIT mutation (R796G) in a sporadically case associated with piebaldism and deafness." (PMID 24000325, 2013). "Genotype association of the PAX3 and KIT variants with DBE, deafness, and white spotting in 299 cats (for coat color patterns of the studied cats)." (PMID 38869246, 2024). "Although the piebald locus is caused by MITF and the merle locus is caused by PMEL in dogs, and the white spotting locus is caused by KIT in cats, the genes responsible for the pigment-associated deafness in these species have not yet been identified." (PMID 26664958, 2015). "Across species, the genes identified with deafness or white pigmentation patterns include MITF, PMEL, KIT, EDNRB, CDH23, TYR, and TRPM1 in dog, cat, horse, cow, pig, sheep, ferret, mink, camelid, and rabbit." (PMID 26664958, 2015). "There was 100% identity in the sequences of the two dogs, suggesting that KIT plays no role in deafness in Dalmatians." (PMID 26664958, 2015).
depression (7 papers, 2011 to 2026). "KIT prevented CORT-induced depression-like behavior, spatial memory impairment, and decreases in hippocampal cell survival, the number of hippocampal new-born immature neurons, accumbal dendritic spine density and GDNF mRNA." (PMID 34765515, 2021).
gastric adenocarcinoma (7 papers, 2013 to 2026). "This together with the absence of c-KIT and PDGFRα mutations in the adenocarcinomas confirm that the major molecular pathways of tumor development are different in gastric adenocarcinomas and adjacent MGs." (PMID 33335133, 2020). "However, gastric adenocarcinomas do not provide a differential diagnostic problem, as they are most usually negative for KIT, DOG1, and CD34, while GISTs are usually positive for at least one of these markers." (PMID 35804982, 2022).
inflammatory myofibroblastic tumor (7 papers, 2014 to 2024). A multinodular intermediate fibroblastic neoplasm that arises from soft tissue or viscera, in children and young adults. "Negative results for DOG-1, CD117 (KIT), CD34, S-100 protein, neurofilament, cytokeratin, epithelial membrane antigen (EMA), and ALK suggest that PF is a distinct disease entity from GIST, angiomyxoma, neurogenic tumor, sarcomatoid carcinoma, and inflammatory myofibroblastic tumor." (PMID 31360694, 2019).
polycythemia vera (7 papers, 2018 to 2025). "HHT, a recognized protein synthesis inhibitor, playing a significant role in the treatment of hematological diseases such as AML, CML, MDS, and polycythemia vera by regulating mechanisms including KIT, MYC, MCL-1 and Cyclin-D1." (PMID 40591114, 2025). "Nevertheless, in a preclinical study, mice with a particular loss-of-function mutation in KIT developed polycythemia vera in addition to GIST, suggesting a function of KIT in early erythropoiesis." (PMID 39165680, 2024).
thyroid nodule (7 papers, 2012 to 2025). A small circumscribed mass in the THYROID GLAND that can be of neoplastic growth or non-neoplastic abnormality. "In this line, this study confirms the diagnostic potential of c-KIT expression as an adjunctive marker in the preoperative management of thyroid nodules." (PMID 28301608, 2017). "In contrast, in the case of PTC, cell dedifferentiation and tumor progression were associated with loss of KIT gene expression, which could be a diagnostic tool for identifying malignant thyroid nodules." (PMID 40725233, 2025). "We previously showed that the expression silencing of KIT gene is associated with the malignant phenotype of thyroid nodules and KIT expression may represent a useful tool in the preoperative management of thyroid lesions." (PMID 22958914, 2012). "We propose the use of BRAF test (after uncertain cytological diagnosis) to assess the malignancy of thyroid nodules at first, then the use of the c-KIT expression to ultimately assess the diagnosis of the nodules that otherwise would remain suspicious." (PMID 22233760, 2012). "A 10-gene (KIT, SYNGR2, C21orf4, Hs.296031, Hs.24183, FAM13A1, C11orf8, KIAA1128, IMPACT, CDH1) and a 6-gene (KIT, LSM7, SYNGR2, C21orf4, Hs.296031, Hs.24183) assays have been proposed to have high diagnostic accuracy to distinguish thyroid nodules." (PMID 22958914, 2012). "Few papers have suggested to analyze KIT expression on FNA biopsies from benign and malignant thyroid nodules to verify if KIT expression analysis is of clinical interest." (PMID 26581891, 2015). "c-KIT expression was analyzed by qPCR in a set of 82 FNAC, histologically diagnosed as 36 benign and 46 malignant thyroid nodules." (PMID 22233760, 2012).
thyroid tumor (7 papers, 2012 to 2025). A benign or malignant neoplasm affecting the thyroid gland. "Few and dated studies have analyzed c-KIT expression profiles in thyroid tumors, finding a correlation with differentiation and growth control of thyroid epithelium and also suggesting a c-KIT loss of function in malignant transformation." (PMID 28301608, 2017). "Few studies investigated the role of c-KIT expression in thyroid tumors, suggesting a role for this receptor and its ligand in differentiation and growth control of thyroid epithelium and a receptor loss following malignant transformation." (PMID 28301608, 2017). "In the present study, we decided to explore the role of c-KIT in thyroid tumor proliferation and differentiation by analyzing two known markers of thyrocytes differentiation: PAX8 (Paired-box gene 8) and TTF-1 (Thyroid transcription factor-1)." (PMID 28301608, 2017). "Several mechanisms have been described that can mediate the downregulation of c-KIT, including dysregulated expression of specific microRNAs (miR-146b, miR-221, and miR-222) and promoter hypermethylation; however, there are no studies that investigate this events in thyroid tumors." (PMID 28301608, 2017).
astrocytoma (6 papers, 2009 to 2024). "In grade 2–3 astrocytoma, variations in FGFR4, KIT, NTRK2, and positive immunohistochemistry for ATRX and EGFR showed statistically significant results in univariate survival analysis." (PMID 38970209, 2024). "By examination using MLPA KIT probemix P105, EGFR amplification was seen in 8 IDH-wild-type astrocytomas (19.0%), comprising 1 DA (5.6%) and 7 AAs (29.2%), tending to be slightly more frequent in AAs than in DAs (p = 0.109)." (PMID 34257410, 2021). "CDKN2A/B deletion was also observed in Res259 astrocytoma cells, which also contained the well-described 4q12 amplicon, resulting in high level gains of the oncogenes PDGFRA and KIT, and low-level gain of a region including KDR/VEGFR2." (PMID 19365568, 2009).
bladder cancer (6 papers, 2015 to 2024). "We first examined CD117/KIT expression in schistosomal and non-schistosomal urinary bladder carcinomas from 60 Egyptian patients." (PMID 37338655, 2023). "Our data from this combined analysis could help us to develop new therapeutic approaches that selectively antagonize CD117/KIT, HER2, and ERβ, or act upon the downstream target genes of these receptors that might be applied individually or in combination to target bladder cancer." (PMID 37338655, 2023).
fibromatosis (6 papers, 2010 to 2022). A poorly circumscribed neoplasm arising from the soft tissues. "Several case reports have suggested a potential role of the KIT M541L variant in the sensitivity of Imatinib for aggressive fibromatosis." (PMID 26572169, 2015). "Here, we describe for the first time a V530I KIT exon 10 mutant that was associated to a dramatic imatinib response in an extraabdominal aggressive fibromatosis." (PMID 20339585, 2010).
hypereosinophilic syndrome (6 papers, 2016 to 2025). Hypereosinophilic syndrome (HES) constitutes a rare and heterogeneous group of disorders, defined as persistent and marked blood eosinophilia and/or tissue eosinophilia associated with a wide range of clinical manifestations reflecting eosinophil-induced tissue/organ damage. "The specific inhibition of PDGFRA, a receptor tyrosine kinase closely related to KIT, induced apoptosis in a hypereosinophilic syndrome (HES) cell line but did not influence on IAP expression." (PMID 27167336, 2016).
idiopathic pulmonary fibrosis (6 papers, 2017 to 2025). Idiopathic pulmonary fibrosis (IPF) is a nonneoplastic pulmonary disease that is characterized by the formation of scar tissue within the lungs in the absence of any known cause. "Imatinib’s robust connectivity with PDGFR and c-KIT indicates its potential efficacy in treating pulmonary fibrosis." (PMID 40732226, 2025).
invasive breast carcinoma (6 papers, 2012 to 2025). A carcinoma that infiltrates the breast parenchyma. "Two extensive studies of 4,444 and 348 cases of invasive breast carcinoma, using c-KIT to stain the mast cells, concluded that stromal mast cells in invasive breast carcinoma were associated with a favourable prognosis." (PMID 37928785, 2023). "Using an unbiased approach, we found that mutations in BRAF, EGFR and KIT are significantly more common in this heavily treated population when compared with the cohort of invasive breast carcinoma patients in The Cancer Genome Atlas (TCGA)." (PMID 28247034, 2017). "CD117 (c-KIT) antibodies were used to stain 160 formalin-fixed and paraffin-embedded invasive breast carcinoma tissues to demonstrate the presence of mast cells." (PMID 37928785, 2023).
kidney cancer (6 papers, 2015 to 2026). Primary or metastatic malignant neoplasm involving the kidney. "Kidney cancer, unlike all other solid cancers, has many negative significant correlation records for KIT expression and immune infiltration signatures, however the possible reason for such a phenomenon is unclear." (PMID 35887076, 2022).
meningioma (6 papers, 2012 to 2025). A generally slow growing tumor attached to the dura mater. "1/7 KIT positive meningiomas showed allele loss corroborated by reduced FISH signal in the corresponding neoplastic tissue." (PMID 22672386, 2012). "KIT immunopositivity was significantly associated with up-regulated transcript levels in meningioma (p < 0.001 for pair wise comparison)." (PMID 22672386, 2012). "In NF2-null meningioma cell lines, kinome profiling revealed activation of Eph receptor tyrosine kinases (EphA2, EphB1), c-KIT, and the Src/SFK pathway, targets of the FDA-approved kinase inhibitor Dasatinib." (PMID 41200151, 2025). "Variants typical for angiomatous (brain) meningioma are PIK3CA, KIT, PTPN11, CDH1, SMAD4, and SMARCB1; the variants typical for psammomatous meningioma are APC, FGFR2, HNF1A, STK11, and JAK3." (PMID 38476782, 2024). "Conclusively, contrary to earlier reports, present study demonstrates KIT immunoexpression in a subset of human meningiomas." (PMID 22672386, 2012). "Particularly, though 1/7 meningioma KIT positive cases showed a transversion (A → C) in exon 10, leading to a mis-sense substitution, (Met → Leu) at codon 541(M541L)." (PMID 22672386, 2012). "In the present study, heat maps were generated using Euclidean distance and complete linkage to hierarchically cluster meningioma cases based on ΔCt values of KIT and KITLG expression (for ΔCt calculation see methods)." (PMID 22672386, 2012). "In the immunopositive meningiomas with up-regulated KIT transcripts, RQ values were found to be in the range of 1.13 to 2.92 (for RQ calculations)." (PMID 22672386, 2012). "Moderate (++) KIT staining was seen in 2/7 meningioma cases, while, strong (+++) expression was detected in 2/7 cases." (PMID 22672386, 2012). "The third study systematically evaluated KIT expression in 37 meningiomas employing a similar staining protocol but a different anti-KIT antibody (MBL, Nagoya, Japan)." (PMID 22672386, 2012). "Contrary to earlier reports, KIT expression, was detected immunohistochemically in 20.6% meningioma cases (n = 34)." (PMID 22672386, 2012). "This study clearly demonstrates KIT over-expression in the human meningiomas." (PMID 22672386, 2012). "Taken together, it would be of interest to pursue whether the enhanced KIT expression in subset of meningioma cases acts as a catalyst in, complicit to or as a consequence of the meningeal neoplastic process." (PMID 22672386, 2012). "Further, it would be vital to determine whether KIT immunopositive meningioma cases, indeed have an activated oncoprotein." (PMID 22672386, 2012). "We indeed observed up-regulated KIT protein and mRNA expression in a subset of meningiomas." (PMID 22672386, 2012). "Thus, KIT is a potential candidate for detailed investigation in the context of meningioma pathogenesis." (PMID 22672386, 2012). "Analysis of KIT in the immunopositive meningioma cases did not reveal loss or gain of function mutations as reported in other pathological conditions." (PMID 22672386, 2012). "KIT immunopositivity was detected in 20.6% (7/34) meningioma cases as opposed to the earlier report of its negligible expression in 37 meningioma cases." (PMID 22672386, 2012). "Meningiomas have been reported to lack KIT expression in three independent studies." (PMID 22672386, 2012). "Of these, one on KIT expression in germinomas randomly included a single meningioma sample." (PMID 22672386, 2012). "Further, with no discernible activating KIT mutations in immunopositive meningioma cases, the receptor could possibly get activated via autocrine and/or paracrine modes in these tumors." (PMID 22672386, 2012). "However, we observed KIT mRNA expression in some meningioma cases." (PMID 22672386, 2012). "Further, interspersed KIT positive mast cells in an otherwise KIT negative meningioma served as an internal control." (PMID 22672386, 2012).